HTR1A (5-hydroxytryptamine receptor 1A)
Diseases named in the same sentence as HTR1A in open-access papers (continued):
Sharing a sentence is not in itself a finding about the gene and the disease.
Anxiety (253 papers, 2006 to 2026). Intense feelings of nervousness, tension, or panic often arise in response to interpersonal stresses. "The reduced anxiety in females differs from the anxiety phenotype seen upon loss of HTR1A repressors Freud-1 and Deaf1." (PMID 29636529, 2018). "Likewise, other genes related to 5-HT signaling, such as htr1a and slc6a4, have also been linked to anxiety-related defensive behavioral responses in rodents." (PMID 38705984, 2024). "This systemic serotonergic enhancement was further supported by the restoration of hippocampal serotonin receptors (HTR1A and 5HT7R), which play crucial roles in mood regulation, anxiety, and stress response." (PMID 41309364, 2025). "Our results show animals fed a HFD had higher expression of tph2, htr1a and slc6a4 in the anxiety-related cDRD subregion." (PMID 38705984, 2024). "Here we conducted a nine-week HFD protocol in male rats, followed by an analysis of the gut microbiome diversity and community composition, brainstem serotonergic gene expression (tph2, htr1a, and slc6a4), and anxiety-related defensive behavioral responses." (PMID 38705984, 2024). "Overall, our results show that a HFD increases tph2, htr1a and slc6a4 mRNA gene expression in areas of the DR, including subregions (e.g. cDRD) involved in the regulation of anxiety-related behaviors." (PMID 38705984, 2024). "Studies in animal models have suggested that anxiety-like behavior can increase when the function of HTR1A (the orthologous human and rodent gene) is eliminated or overexpressed." (PMID 37240050, 2023). "Genetic studies in animal models have suggested that anxiety-like behavior can increase when the HTR1A function is eliminated or overexpressed." (PMID 33178009, 2020). "For example, knockout of the HTR1A repressor Deaf1 results in increased 5-HT1A autoreceptor expression but greater functional uncoupling in females, and a sex- and test-dependent anxiety phenotype." (PMID 31114473, 2019). "Altogether, these findings suggest that the effects of life history on anxiety-like behaviour are mediated, at least partly, by changes in the regulation of serotonergic pathways, especially reflected by differential Htr1a and Maoa expression." (PMID 28821809, 2017). "Not consistent with these previous findings, we found that Htr1a was positively correlated with anxiety-like behavior in XY mice and gonadal males." (PMID 24199867, 2013). "For instance, while Pdyn is the only gene positively correlated with anxiety-like behavior in XX mice, Htr1a, Cdk5, Adcy2, Akt1, Akt2, and Akt3 positively correlate with anxiety-like behavior in XY- mice." (PMID 24199867, 2013). "A study on 5-HT1A (HTR1A) found that rs6295 promoter polymorphisms were associated with anxiety phenotypes, and loss and blockade of 5-HT1A heterogeneous receptors were observed to increase anxiety and block SSRI efficacy in animal models." (PMID 37581520, 2024). "Moreover, alterations of anxiety-like behaviors were observed in 5-HT1A or 5-HT2A knock-out mouse lines (Htr1a or Htr2a)." (PMID 32594910, 2020). "In addition, cyclic AMP-responsive element-binding protein (CREB) has been suggested to be crucial for the role of HTR1A in modulating anxiety-related behaviors via mediating hippoacampus structural plasticity." (PMID 33178009, 2020). "Moreover, while complete deletion of both receptors in Htr1a/1b-/- mice affected the acute response to SSRIs in the forced swim test, the chronic effects of SSRIs were still observed in anxiety test." (PMID 30618598, 2018). "Htr1a controls serotonin presynaptic release and contributes to postsynaptic signaling, and reduced or lack of expression is associated with increased anxiety-like behaviors." (PMID 24199867, 2013). "Thus, in the present study, we investigated the effects of a HFD treatment for 9 weeks on the gut microbiome, expression of tph2, htr1a and slc6a4 genes in the brainstem raphe nuclei, and anxiety-related defensive behavioral responses in adult male Wistar rats." (PMID 38705984, 2024).
Anxiety (continued). "As HTR1A typically has an inhibitory effect on serotonin production, having fewer of them would result in increased serotonergic signaling, which explains the higher levels of explorative and social personality profiles in these chimpanzees through serotonin-induced anxiety relief." (PMID 36421387, 2022). "The importance of maintaining constant expression of HTR1A in prefrontal cortex during development should not be underestimated, since conditional loss of the forebrain Htr1A receptor during development leads to life-long abnormal anxiety behaviour." (PMID 21829518, 2011). "Increased expression of tph2, htr1a, and slc6a4 in the cDRD of HFD-fed rats is consistent with previous studies implicating the cDRD in chronic (even lifelong) anxiety-like states, and vulnerability to future stress exposures in adulthood." (PMID 38705984, 2024). "HTR1A, HTR1B, HTR2A, and HTR2B were commonly targeted in preclinical studies for the anxiety treatment as well as the anxiolytic-like studies of SZJ." (PMID 33178009, 2020). "Generally, the activation of HTR1A, HTR2A receptors can produce anxiolytic effects, whereas inactivation of them increases anxiety-like behaviors." (PMID 33178009, 2020). "More polymorphisms in the Htr1a gene exist, but it is not clear whether they influence anxiety." (PMID 23781201, 2013). "Currently, though the alteration of GABAA and 5-HT receptors under strong oxidative stimulation is unclear, our result in some extent suggested that overexpression of GABRA1, GABRA2, HTR1A, HTR1B, and HTR2A may be involved in oxidative stress-induced anxiety." (PMID 33178009, 2020).
schizophrenia (81 papers, 2011 to 2025). A major psychotic disorder characterized by abnormalities in the perception or expression of reality. "Notably, our previous case-control experiment revealed that the human HTR1A gene polymorphism rs113195492 (−1068G/A) G allele might be a susceptibility gene in female paranoid schizophrenia." (PMID 30594152, 2018). "Hypomethylation in the promotor region of the serotonin receptor type-1 gene (HTR1A) gene in blood samples of schizophrenia patients has been reported, suggesting the involvement of the serotonin pathway in the disease." (PMID 34299291, 2021). "The present study investigated the association of nine polymorphisms in the four 5-hydroxytryptamine receptor (HTR) genes HTR1A, HTR2A, HTR3A, and HTR2C and the gene encoding for the serotonin transporter SLC6A4 with MetS in patients with schizophrenia." (PMID 33807811, 2021). "We investigated the associations of DRD3 rs6280, HTR1A rs6295, BDNF rs6265, SCL6A4 rs16965628, and 5HT2A rs7322347 with schizophrenia in a case–control study, and associations of these genetic variants with several clinical features." (PMID 34025476, 2021). "The present paper describes the results of an association study of in the end 24 polymorphic variants of HTR1A, HTR1B, HTR2A, HTR2C, HTR3A, HTR3B, and HTR6 genes with TD and two of its subtypes in 449 patients with schizophrenia." (PMID 32390801, 2020). "This study aimed to examine molecular associations of HTR1A, HTR1B, HTR2A, HTR2C and HTR6 gene polymorphisms with acute EPS in 229 male schizophrenia patients, following two weeks of haloperidol monotherapy." (PMID 32231051, 2020). "For cognitive function in patients with schizophrenia, the dopamine neurotransmitter in the prefrontal cortex plays a crucial role, and the HTR1A gene interacts with the COMT gene to regulate the function of the dopamine system." (PMID 30766477, 2019). "HTR1A is additionally linked to its paralog HTR2A, a known susceptibility gene for schizophrenia, via GO annotations on serotonin binding activity." (PMID 21696594, 2011). "A functional polymorphism, rs6295 in the 5-HT1A receptor gene (HTR1A), is known to be associated with the negative schizophrenia symptom response to antipsychotic medication." (PMID 36979236, 2023). "However, Lopez-Figueroa and Selvaraj observe an alteration in HTR1A mRNA levels in the prefrontal cortex of individuals with schizophrenia." (PMID 37990254, 2023). "It has been reported that HTR1A affects the occurrence of several diseases including periodic fever, menstrual cycle-dependence febrile episode, generalized anxiety disorder, and schizophrenia." (PMID 37161455, 2023). "In addition to HTR1B, other 5-HT receptors, including HTR1A, HTR2A, HTR3, HTR4, and HTR6 are associated with schizophrenia." (PMID 37990254, 2023). "At present, studies on the functional sequences and polymorphisms of the HTR1A gene 5′-regulatory region involved in schizophrenia were not comprehensive and the conclusions remained controversial." (PMID 30594152, 2018). "We aimed to examine the association of HTR1A and HTR5A with schizophrenia and executive function." (PMID 27897266, 2016). "Although our integrated disease-gene databases (OMIM Morbid Map and CTD) have not indexed HTR1A as a schizophrenia susceptibility gene, variants in the gene have previously been shown to be associated with schizophrenia and other psychopathologies." (PMID 21696594, 2011). "In addition, association studies between genetic variants of the HTR1A, as well as solute carrier family 6, member 4 (SLC6A4) genes and clinical outcomes in schizophrenia, have shown that rs6295 and 5-HTTLPR polymorphisms significantly influence clinical symptoms in schizophrenia." (PMID 36983018, 2023). "Interestingly, there appears to be an increase in HTR1A expression and binding in schizophrenia." (PMID 21829518, 2011).
schizophrenia (continued). "The aim of this study was to research the associations between symptomatology and SNP of genes related to the systems of neurotransmission (DRD3 rs6280, HTR1A rs6295, 5HT2A rs7322347) and neurotrophic factor (BDNF rs6265) in schizophrenia patients." (PMID 34025476, 2021). "A set of 29 SNPs of genes of serotonin receptors HTR1A, HTR1B, HTR2A, HTR2C, HTR3A, HTR3B, and HTR6 was studied in a population of 449 Caucasians (226 females and 223 males) with verified clinical diagnosis of schizophrenia (according to ICD-10: F20)." (PMID 32390801, 2020). "Our results provide further supportive evidence of the effect of HTR1A and HTR5A on the etiology of schizophrenia and suggest that the selected genetic variations in HTR5A may be involved in impaired executive function." (PMID 27897266, 2016). "However, we did not observe any differences in the mRNA expression of HTR1A and HTR2A in schizophrenia, consistent with the findings of Wysokinski and colleagues." (PMID 37990254, 2023).
anxiety disorder (32 papers, 2013 to 2025). A category of psychiatric disorders which are characterized by anxious feelings or fear often accompanied by physical symptoms associated with anxiety. "HTR1A, a key player in serotonin regulation, is implicated in mood and anxiety disorders, preserving mood stability and cognitive functioning." (PMID 38924082, 2024). "HTR1A C-1019G polymorphism has been widely investigated as the 5-HT1A receptor has been considered to be strongly involved in the pathophysiology of depressive and anxiety disorders." (PMID 28951738, 2017).
cognitive deficits (28 papers, 2009 to 2025). "However, FMT in the Sham group only rescued the expressions of cn1r, cn2r, and htr1a, indicating that the interaction between gut microbiota and eCB system plays a pivotal role in the pathogenic processes in CNP and its associated cognitive deficits." (PMID 35058749, 2021).
mood disorder (23 papers, 2014 to 2025). A cognitive disorder a disturbance in which the person's mood is hypothesized to be the main underlying feature. "There is a report indicating that 5-hydroxytryptamine receptor 1A encoded by HTR1A is recognized to correlate cardiometabolic diseases risk and mood disorders." (PMID 34012683, 2021). "Serotonin is responsible for regulating a wide variety of mood disorders, mostly through the action of serotonin receptors (HTR1A and HTR2A) and serotonin transporter (SERT)." (PMID 39202385, 2024).
epilepsy (16 papers, 2013 to 2025). A brain disorder characterized by episodes of abnormally increased neuronal discharge resulting in transient episodes of sensory or motor neurological dysfunction, or psychic dysfunction. "The polymorphism rs6295 (−1019G/C) G allele resulted in a decrease in the HTR1A mRNA level in the hippocampus of patients with epilepsy by altering the binding intimacy of the c-Jun transcription factor." (PMID 30766477, 2019).
insomnia (14 papers, 2021 to 2025). A sleep disorder characterized by difficulty in falling asleep and/or remaining asleep. "In addition, 5-HT1A (HTR1A) and 5-HT2A (HTR2A) have been identified as common targets for the treatment of insomnia, in both clinical and basic studies, as well as prevenient studies of ZSS for the treatment of insomnia." (PMID 35002696, 2021).
Obesity (9 papers, 2012 to 2024). Accumulation of substantial excess body fat. "In humans, genetic studies have reported that polymorphisms in Htr genes (for example, HTR1A, HTR1Dβ, and HTR2A) are associated with obesity." (PMID 33692832, 2021).
mental disorder (7 papers, 2011 to 2025). A disease that has its basis in the disruption of mental process. "HTR1A and HTR2A have also been studied in relation to mental disorders." (PMID 21448266, 2011).
bipolar depression (6 papers, 2017 to 2025). "Our network pharmacology‐based analysis suggests that lurasidone‐induced manic switching in bipolar depression may be associated with the modulation of HTR1A and HTR7, possibly through a mechanism similar to that of asenapine." (PMID 40202273, 2025). "Supporting a developmental origin of these changes, several linkage studies have described an association between bipolar disorder and single nucleotide polymorphisms in genes such as TPH2, HTR1A, HTR2A, HTR2C or SLC6A450–55." (PMID 30087403, 2018). "While HTR1A, HTR2A, and HTR7 are known targets of lurasidone, MAOB, HTR3A, SLC18A2, and HTR1B were identified for the first time as targets of lurasidone potentially involved in its associated induction of acute manic episodes in people with bipolar depression." (PMID 40202273, 2025). "This study revealed that lurasidone may regulate the serotonergic synapse signaling pathway by interacting with the identified core targets MAOB, HTR1A, HTR2A, HTR3A, SLC18A2, HTR1B, and HTR7 to induce treatment‐emergent mania in people with bipolar depression." (PMID 40202273, 2025). "Our bioinformatics and computational analyses demonstrated that lurasidone may regulate the serotonergic synapse signaling pathway by targeting proteins such as MAOB, HTR1A, HTR2A, HTR3A, SLC18A2, HTR1B, and HTR7 to induce treatment‐emergent mania in people with bipolar depression." (PMID 40202273, 2025).
breast carcinoma (5 papers, 2020 to 2025). "Our earlier research recognized HTR1A as a prognostic biomarker for breast cancer patients and HTR1A agonists have shown notable antitumor activity in murine models of triple-negative breast cancer." (PMID 39766808, 2024). "Breast cancer patients with higher transcription levels of HTR1A/1B/1D/1E/1F/2A/2B/2C/3A/3B/3C/4/5A/6/7 were significantly associated with longer RFS." (PMID 37795441, 2023). "After combining functional experiments with online database analysis, HTR1A (5‐hydroxytryptamine receptor 1A) was selected with antitumor potential in breast cancer cells." (PMID 35199941, 2022). "The results showed that compared with adjacent normal breast tissues, HTR1A CpG sites cg04694812, cg04427003, and cg04799838 in breast cancer tissues showed significantly higher methylation levels (all p < 0.05)." (PMID 35199941, 2022). "The clinical analysis indicates HTR1A as an independent prognostic factor for patients with breast cancer and higher expression indicates better survival." (PMID 35199941, 2022). "We also found that HTR1A overexpression significantly inhibited the proliferation of breast cancer cells, while knockdown showed the opposite trend." (PMID 35199941, 2022). "Immunofluorescence staining of F‐actin showed that HTR1A inhibited the formation of pseudopodia and resulted in a round and blunt appearance and decreased the metastatic potential of breast cancer cells." (PMID 35199941, 2022). "The Oncomine database indicated that the expression level of HTR1A in metastatic breast cancer was lower than that in primary breast cancer (p ≤ 1 ×10−4, fold change ≥ 2, respectively)." (PMID 35199941, 2022). "Treatment with the TβRII inhibitor LY2109761 also rescued the effect of HTR1A knockdown on TβRII/p‐Smad3 expression and the migration ability of breast cancer cells." (PMID 35199941, 2022). "After combining functional experiments with online database analysis, 5‐hydroxytryptamine receptor 1A (HTR1A is selected with antitumor potential in breast cancer cells in vivo and in vitro." (PMID 35199941, 2022). "In addition, paired TNBC and paracancerous tissue showed that the mRNA expression level of HTR1A in breast cancer tissues was significantly lower than that in normal breast tissues (p < 0.0001)." (PMID 35199941, 2022). "Furthermore, treatment with the TβRII agonist TGF‐β1 rescued the reduced expression of TβRII and p‐Smad3 as well as the migration ability of breast cancer cells mediated by HTR1A overexpression." (PMID 35199941, 2022). "We speculated that HTR1A regulates breast cancer progression and metastasis by promoting the protein degradation of TβRII." (PMID 35199941, 2022). "In addition, a cloning assay showed that HTR1A significantly inhibited the clone formation ability of breast cancer cells." (PMID 35199941, 2022). "Furthermore, the demethylation drug 5‐aza‐2′‐deoxycytidine (1 × 10−6m, 5‐AZA‐CdR, ZdCyd, decitabine) was utilized for 7 d, after which the expression of HTR1A was significantly upregulated in breast cancer cells (all p < 0.01)." (PMID 35199941, 2022). "In addition, all breast cancer patients with higher expression of HTR1A showed significantly longer OS and RFS." (PMID 35199941, 2022). "Furthermore, univariate and multivariate analyses showed that HTR1A expression was an independent prognostic factor of RFS in breast cancer patients and a high expression level suggested better survival." (PMID 35199941, 2022). "In addition, HTR1A is an independent predictive factor for breast cancer patients." (PMID 35199941, 2022). "The expression level of HTR1A/1B/2A/2B/2C/4 and HTR7 was significantly negatively related to highly malignant breast cancer types." (PMID 39766808, 2024). "The expression levels of HTR1A, HTR1B, HTR2A, HTR2B, HTR2C, HTR4, and HTR7 were significantly downregulated in highly malignant breast cancer types." (PMID 37795441, 2023).